CASP5 (caspase 5)
Description:
Thiol protease that acts as a mediator of programmed cell death. Initiates pyroptosis, a programmed lytic cell death pathway through cleavage of Gasdermin-D (GSDMD): cleavage releases the N-terminal gasdermin moiety (Gasdermin-D, N-terminal) that binds to membranes and forms pores, triggering pyroptosis. Also mediates cleavage and maturation of IL18. Cleavage of GSDMD and IL18 is not strictly dependent on the consensus cleavage site but depends on an exosite interface on CASP4. During non-canonical inflammasome activation, cuts CGAS and may play a role in the regulation of antiviral innate immune activation.
Synonyms: ICE(rel)III; ICEREL-III; ICH-3
Tractability: Small molecule: a drug acting on it is in phase 2 or 3 trials; a high-quality ligand is known. PROTAC: ubiquitination databases record sites on it; a small molecule that binds it is known.
Target class: Cysteine protease; Protease; Cysteine protease CD clan; Enzyme; Cysteine protease C14 family
Gene: Protein-coding gene on chromosome 11 (104,992,636 to 105,023,168, reverse strand). Ensembl gene ENSG00000137757.
Pathways (Reactome):
Immune System: CASP5 inflammasome assembly; CASP5-mediated substrate cleavage
Programmed Cell Death: Pyroptosis
Gene Ontology:
Molecular function: cysteine-type endopeptidase activity; protein binding; cysteine-type peptidase activity
Biological process: cellular response to mechanical stimulus; protein maturation; substantia nigra development; apoptotic process; non-canonical inflammasome complex assembly; positive regulation of inflammatory response; positive regulation of neuron apoptotic process; proteolysis; regulation of apoptotic process
Cellular component: NLRP1 inflammasome complex; cytoplasm; cytosol
Genetic constraint (gnomAD): Loss-of-function variants: 23 observed, 31.22 expected, observed/expected ratio (o/e) 0.74, 90% interval 0.53 to 1.04. The upper end of that interval is the gene's LOEUF score, 1.04, which puts it in group 4 of 6, group 1 being the genes least tolerant of losing a copy. Missense variants: 388 observed, 414.06 expected, observed/expected ratio (o/e) 0.94, 90% interval 0.86 to 1.02. Synonymous variants: 161 observed, 147.35 expected, observed/expected ratio (o/e) 1.09, 90% interval 0.96 to 1.25.
Homologues: Orthologues: chimpanzee CASP5 (97% identical), macaque CASP5 (76% identical), Caenorhabditis elegans ced-3 (21% identical), zebrafish casp8 (18% identical), tropical clawed frog casp8 (17% identical), Caenorhabditis elegans csp-1 (16% identical), Drosophila melanogaster Dronc (16% identical), Caenorhabditis elegans csp-2 (16% identical), zebrafish casp20 (16% identical), Drosophila melanogaster Decay (14% identical), tropical clawed frog XB5812047 (12% identical), zebrafish casp3l (9% identical), and 1 more. Paralogues in human: CASP4 (64% identical), CASP1 (43% identical), CASP12 (38% identical), CASP2 (20% identical), CASP9 (18% identical), CASP10 (18% identical), CASP3 (18% identical), CASP8 (17% identical), CASP7 (16% identical), CASP6 (15% identical), CFLAR (15% identical), CASP14 (13% identical), and 4 more.
Diseases named in the same sentence as CASP5 in open-access papers:
CASP5 is named in the same sentence as 82 diseases in open-access papers, as found by Europe PMC text mining. Sharing a sentence is not in itself a finding about the gene and the disease. The quoted sentences say what the papers report.
glioma (9 papers, 2019 to 2023). A benign or malignant brain and spinal cord tumor that arises from glial cells (astrocytes, oligodendrocytes, ependymal cells). "CASP5 is significantly differentially expressed in different grades of gliomas and different prognoses." (PMID 36820395, 2023). "In fact, 15 differentially expressed genes, including caspase-5, were upregulated in glioma tissues (n = 667) compared with those in normal brain tissues (n = 1152), suggesting a prognostic value for the pyroptosis-related gene signature in glioma." (PMID 37723542, 2023). "Furthermore, the expression levels of genes encoding NLR proteins (NLRP12, NOD2, NOD1, NLRC4, and NAIP), inflammasome adaptor molecules (PYCARD), and proinflammatory caspases (CASP1, CASP4, and CASP5) were significantly higher in glioma patients than in normal controls." (PMID 31133717, 2019). "One limitation in the research on the non-canonical pathway is that caspase-4 and caspase-5, the key regulators of the non-canonical inflammasome, have not yet been explored in gliomas; thus, functional studies on these are urgently required." (PMID 37723542, 2023). "Of the 11 pyroptosis regulators, 8 revealed remarkable distinctions between glioma and normal tissues, while CASP5, CASP8, and GSDMC did not." (PMID 35620284, 2022). "However, the roles of CASP4 and CASP5 in gliomas has not been reported." (PMID 36861130, 2023).
lung carcinoma (8 papers, 2018 to 2023). "Mutations in CASP5 gene have been associated with several types of cancer such as leukemia, endometrial cancer, lung cancer, gastrointestinal tract and colorectal cancers." (PMID 34895171, 2021). "Studies have reported that caspase-5 is associated with various malignancies, including gastric cancer, cervical cancer, lung cancer, and human glioblastoma." (PMID 34899864, 2021). "Among the genotypes possibly associated with lung cancer risk were Val318Leu of the CASP-5 gene (OR = 2.47, 95% CI: 1.07–5.69, p = 0.03), Lys441Arg of the DR4 gene (OR = 1.89, 95% CI: 1.05–3.40, p = 0.03), and His302Asp for CASP-8 (OR = 2.26, 95% CI: 1.18–4.31, p = 0.02)." (PMID 33800294, 2021). "Compared with the control group, the GSDMD, CASP4 and CASP5 expression in PBMCs of lung cancer patients was significantly higher(P < 0.05)." (PMID 37194012, 2023). "CASP5 is reportedly related to different cancers, such as cervical cancer, osteosarcoma, lung cancer, and human glioblastoma." (PMID 36552744, 2022). "As for Caspase-5, it might be a suppressor gene of highly metastatic potential in lung cancer." (PMID 37194062, 2023).
psoriasis (8 papers, 2017 to 2025). An autoimmune condition characterized by red, well-delineated plaques with silvery scales that are usually on the extensor surfaces and scalp. "Therefore, the factors, including IL-17A, IL-22, IL-1β, NLRC4, MEFV, and CASP5, detected by ocular surface test in our case should be verified for their usefulness as biomarkers for psoriasis-associated conjunctivitis in clinical studies involving a large number of cases." (PMID 40861543, 2025). "Given this critical role of CASP1 in amplifying inflammation, and the fact that CASP5 is similarly involved in downstream pyroptotic signaling, targeting CASP1 and CASP5 emerges as the most effective strategy to mitigate the inflammatory response in psoriasis." (PMID 40771724, 2025). "To explore the therapeutic potential of targeting these hub genes in alleviating psoriasis, we used Lipid Nanoparticles (LNPs) to deliver gRNAs targeting Casp1 and Casp5 to keratinocytes in the IMQ-induced psoriasis mouse model." (PMID 40771724, 2025). "Building on these insights, we sought to test the therapeutic potential of targeting key pyroptosis-related genes, specifically CASP1 and CASP5, in the treatment of psoriasis." (PMID 40771724, 2025). "We employed CRISPR-Cas9 gene editing, delivered via lipid nanoparticles (LNPs), to selectively knock out Casp1 and Casp11 (murine homolog of human CASP5) in keratinocytes within the IMQ-induced psoriasis mouse model." (PMID 40771724, 2025). "The non-classical pathway of pyroptosis mediated by caspase-4 and caspase-5 was identified as kernel regulators in psoriasis by a random forest algorithm in the current study." (PMID 36110207, 2022). "Here, immunofluorescent staining illustrated the increased expression of caspase-5 in psoriasis and showed a prominent distribution throughout the layers of the psoriatic epidermis compared to healthy skin." (PMID 28422993, 2017). "Patients suffering from psoriasis have lower vitamin D levels, and we observed that application of vitamin D suppresses caspase-5 in keratinocytes in psoriasis." (PMID 28422993, 2017). "Among the investigated key cytokines relevant in psoriasis, IFNγ was detected as the main inducing factor for inflammatory caspase-5 besides caspase-1 in keratinocytes, whereas IL-17A had an amplifying effect." (PMID 28422993, 2017). "Together, this study identified disease-intrinsic regulators, triggers and therapeutic mechanisms of caspase-5 dependent epidermal IL-1β production in psoriasis." (PMID 28422993, 2017). "Corresponding skin sections of psoriasis showed a reduced epidermal thickening in response to calcipotriol which is accompanied by an attenuated caspase-5 staining in the epidermis." (PMID 28422993, 2017). "Here, we investigate regulators and triggers for epidermal NLRP1-dependent caspase-5 activation in a psoriasis-relevant cytokine micro-milieu." (PMID 28422993, 2017). "Here, our data indicate that vitamin D further acts as a direct suppressor of caspase-5 and IL-1β production in keratinocytes suggesting a novel anti-inflammatory mechanism relevant in psoriasis and other Th17-driven inflammatory skin diseases." (PMID 28422993, 2017). "This was further supported by immunoblot analysis from corresponding skin biopsies showing reduced caspase-5 levels in psoriasis by calcipotriol (0.8-fold)." (PMID 28422993, 2017). "Another paper reported on the expression and activity of caspase-5 in psoriasis." (PMID 38785927, 2024). "A downregulation in CASP5 mRNA expression was observed in the lesional skin of psoriasis patients treated with a TNF inhibitor compared to their skin lesions before the start of the respective therapy, indicating a prevention of TNF-induced inflammasome priming." (PMID 37325658, 2023). "Here, we observed elevated epidermal expression and increased caspase-5 activation in psoriasis." (PMID 28422993, 2017).
psoriasis (continued). "Notably, CASP1 and CASP5 were highlighted as central downstream effectors of pyroptosis, making them attractive therapeutic targets for modulating skin inflammation and hyperplasia in psoriasis." (PMID 40771724, 2025). "Further, inflammatory pro-caspase-5 and cleaved caspase-5 could be detected in psoriatic lesions suggesting that caspase-5 activity is regulated by an autoinflammatory micro-milieu in epidermal keratinocytes in psoriasis." (PMID 28422993, 2017). "In this study, we provide a comprehensive analysis of pyroptosis-related genes (PRGs) in psoriasis, identifying key molecular players such as CASP1, CASP5, AIM2, NOD2, and IL1B that drive the inflammatory response and disease progression." (PMID 40771724, 2025). "Our analysis identified CASP1, CASP5, AIM2, NOD2, GZMB, GZMA, and IL1B as key hub genes in the inflammatory pathways driving psoriasis pathogenesis." (PMID 40771724, 2025). "While our study provides compelling evidence for the role of pyroptosis in psoriasis and the potential of CASP1 and CASP5 as therapeutic targets, several questions remain to be addressed." (PMID 40771724, 2025). "Our findings underscore the critical role of pyroptosis in psoriasis pathogenesis and demonstrate that targeting CASP1 and CASP5 through CRISPR-Cas9 gene editing can effectively alleviate disease symptoms and reduce inflammation in the IMQ-induced mouse model." (PMID 40771724, 2025). "Caspase-5 mRNA is upregulated 20-fold in lesional skin as compared to nonlesional skin in patients with psoriasis." (PMID 38785927, 2024). "The non-canonical inflammasome component CASP5 was also found upregulated on mRNA level in lesional psoriatic skin compared to non-lesional skin of psoriasis patients and healthy skin." (PMID 37325658, 2023). "Additionally, we targeted CASP1 and CASP5 using CRISPR-Cas9 delivery via lipid nanoparticles (LNPs) to selectively knock out these genes in keratinocytes, resulting in significant therapeutic effects in the IMQ-induced psoriasis mouse model." (PMID 40771724, 2025). "A scattered single cell stain in the psoriatic dermis might be indicative for caspase-5 expressing immune cells, such as macrophages, which could contribute to the caspase-5 levels detected in lesional psoriasis, also after vitamin D treatment (not shown)." (PMID 28422993, 2017). "Our observations on an enhanced caspase-5 regulation in the presence of IL-17A and NLRP1 inflammasome activity in keratinocytes suggests a functional contribution for epidermal IL-1β production in psoriasis and likely other diseases, where Th17 may also contribute, such as lupus erythematosus." (PMID 28422993, 2017). "Interleukin 1 beta (IL-1β) was the most prominent pyroptosis eigengene of psoriasis, followed by absent in melanoma 2 (AIM2) and caspase 5 (CASP5)." (PMID 36110207, 2022).
colon carcinoma (4 papers, 2015 to 2022). "For instance, CASP3 knockout in colon cancer cells showed less invasion and metastases, while the up-regulation of CASP5 was observed in clear cell renal cell carcinoma." (PMID 35928267, 2022). "We thus compared with the same gene expressions (up-regulated transcripts: SLC16A4, DSC3, ALDOB, EPHX4, ARHGAP24; and down-regulated transcripts (MS4A12, TMIGD1, CASP5) in 5 colon cancer lines: HCT 116, Caco2, HT-29, Lovo, and C32." (PMID 25929336, 2015). "Although CASP7 was decreased in colon cancer as a consequence of gene deletion, no data was available for the CASP5 or CD27 genes, while BCL2 was over-expressed in cancer tissue." (PMID 28962550, 2017).
COVID-19 (4 papers, 2021 to 2024). A disease caused by infection with severe acute respiratory syndrome coronavirus 2. "We mined available clinical data and found that the expression of human CASP4 and CASP5 in COVID-19 testing swab material correlates with the severity of SARS–CoV-2 infection." (PMID 35588457, 2022). "The increased expression of selected IFN-I (OAS1, OAS2, and IFIT1) and inflammasome related genes (CASP1, CASP5, NLRC5 and NAIP) between COVID-19 and HC PMNs was confirmed by RT-qPCR." (PMID 39172744, 2024).
gastric cancer (4 papers, 2021 to 2023). A primary or metastatic malignant neoplasm involving the stomach. "We investigated that PLCG1, CASP5, CASP8 and NLRP3 displayed the highest mutation frequencies in gastric cancer specimens." (PMID 37595258, 2023). "For instance, CASP5 expression was related to favorable overall survival in gastric cancer." (PMID 35255915, 2022).
renal carcinoma (4 papers, 2009 to 2023). A carcinoma arising from the epithelium of the renal parenchyma or the renal pelvis. "The strongest individual SNP association with renal cancer was observed with rs507879, located within exon 2 of CASP5 and results in a missense mutation and amino acid substitution (Thr90Ala)." (PMID 19603096, 2009). "We observed that individuals with CASP1/5/4/12 haplotype (spanning area upstream of CASP1 through exon 2 of CASP5) GGGCTCAGT were at higher risk of renal cancer compared to individuals with the most common haplotype (OR:1.40, 95% CI:1.10–1.78, p-value = 0.007)." (PMID 19603096, 2009). "In summary, the results from this study suggest that genetic polymorphisms and haplotypes within the CASP1, CASP5, EGFR, and IGFBP3 genes are associated with renal cancer risk." (PMID 19603096, 2009). "In conclusion, our evaluation has identified common genetic variants in CASP1, CASP5, EGFR, and IGFBP3 that could be associated with renal cancer risk." (PMID 19603096, 2009). "Of these, several genes including CASP5, RAP1GAP, and GREM1 have been reported to be involved in the pathogenesis of renal cancer or significant in predicting overall survival, suggesting that the present analysis using the TCGA database has potential prognostic value." (PMID 32952743, 2020).
bladder cancer (3 papers, 2019 to 2022). "CASP5 was also found to be associated with bladder cancer development, especially in the selected cases with smoking exposure." (PMID 31886185, 2019).
glioblastoma (3 papers, 2021 to 2022). The most malignant astrocytic tumor (WHO grade IV). "Conversely, higher expression levels of GSDMB, GZMA, and GZMB were detected in T cells, whereas NLR4 and CASP5 showed specifically high expression levels in TAMs, and CASP5, GZMA, GZMB, and NLRC4 were barely detected in glioblastoma cells." (PMID 35990696, 2022).
melanoma (3 papers, 2019 to 2024). A malignant, usually aggressive tumor composed of atypical, neoplastic melanocytes. "We found that some inflammasome genes, including CARD domain containing 4 (NLRC4), caspase 5 (CASP5), absent in melanoma 2 (AIM2) and the already mentioned NLRP3, were upregulated in our data." (PMID 30935390, 2019).
Sepsis (3 papers, 2023 to 2024). Sepsis is defined as life-threatening organ dysfunction caused by a dysregulated host response to infection. "We report that CASP4 and CASP5 are differentially regulated during acute-on-chronic liver failure and sepsis-associated immunosuppression, suggesting non-redundant functions in the inflammasome response to infection." (PMID 38106412, 2023). "Moreover, differences in the expression of CASP1, CASP3, CASP4, and CASP5 could help distinguish the level of immune cell infiltration in sepsis." (PMID 37939116, 2023). "Accordingly, the contribution of caspase-5 to the defense against Gram-negative bacteria and to the response to LPS in sepsis are only incompletely understood at present." (PMID 38785927, 2024). "We summarize the interspecies differences and the evolution of pro-inflammatory caspases in mammals and discuss the potential roles of caspase-5 in the defense against Gram-negative bacteria and in sepsis." (PMID 38785927, 2024). "To understand the role played by the non-canonical inflammasome in this context, we examined CASP4 and CASP5 expression in monocytes from patients with sepsis and organ damage who did or did not exhibit ET." (PMID 38106412, 2023). "Our analysis of human monocytes/PBMCs from two independent cohorts of critically ill patients with severe infection illustrates a specific down-regulation of caspase-4, not caspase-5, in sepsis and ACLF." (PMID 38106412, 2023). "In this study, we have explored the regulation of non-canonical inflammasome constituents CASP4, CASP5 and GSDMD during sepsis and acute-on-chronic liver failure (ACLF)-associated immunosuppression." (PMID 38106412, 2023).
acute kidney injury (2 papers, 2022). Sudden and sustained deterioration of the kidney function characterized by decreased glomerular filtration rate, increased serum creatinine or oliguria. "Indeed, another study shows that danger signals from necrotic tubular epithelial cells could activate the NOD-like receptor protein 3 (NLRP3) inflammasome in macrophages through the TLR2/caspase 5/Panx1 axis during acute kidney injury (AKI)." (PMID 36555574, 2022).
breast carcinoma (2 papers, 2010 to 2013). "In breast cancer, the strongest associations included either SNPs in or gene burden scores for genes LDLRAD1, SLC19A1, FGFBP3, CASP5, MMAB, SLC16A6, and INS-IGF2." (PMID 23555315, 2013).
endothelial dysfunction (2 papers, 2025). In vascular diseases, endothelial dysfunction is a systemic pathological state of the endothelium (the inner lining of blood vessels) and can be broadly defined as an imbalance between vasodilating and vasoconstricting substances produced by (or acting on) the endothelium. "WGCNA prioritized the MEbrown module, enriched in inflammation-related genes (e.g., TNFRSF25, CASP5), which aligns with prior work linking TNF receptor superfamily members to endothelial dysfunction." (PMID 40826682, 2025).